H2AX (H2A.X variant histone)
Diseases named in the same sentence as H2AX in open-access papers (continued):
Sharing a sentence is not in itself a finding about the gene and the disease.
colon carcinoma (39 papers, 2009 to 2024). "The results showed that 17-AAG in combination with PL caused an obvious increase of nuclear γ-H2AX foci in colon cancer cells." (PMID 37833257, 2023). "In our study, we found that POU2F1 or ALDOA over-expression not only reduced intracellular ROS, but also decreased γ-H2AX, a hallmark of DNA damage-related apoptosis in colon cancer cells." (PMID 34997215, 2022). "Acute exercise also increased serum IL‐6, and stimulating colon cancer cells with recombinant IL‐6 reduced intracellular γ‐H2AX expression and cell proliferation in a dose‐dependent manner, mimicking the effect of exercise." (PMID 35213038, 2022). "We found that the exercise‐induced reduction in colon cancer proliferation was accompanied by decreased levels of intracellular γ‐H2AX, indicating a reduction in DNA damage." (PMID 35213038, 2022). "In all colon cancer cell lines tested, Xn at very low concentrations of 2.5–10 μM induces a strong increase in phosphorylated-histone H2AX (γ-H2AX), which reflects DNA damage levels at 24 h and 48 h." (PMID 32290112, 2020). "In conclusion, we showed for the first time that bigelovin induced ROS and increased DR5 expression, which in turn activated downstream caspase and caused G2/M arrest and DNA damage through regulating p21, p-Rb and p-H2AX expressions in colon cancer cells." (PMID 28181527, 2017). "A positive collaboration between fibronectin and γ‐H2AX was previously reported in human colon cancer cells." (PMID 26750654, 2016). "Recently, we showed that deficiency in the DNA repair histone variant H2AX in colon cancer cells led to chromatin remodeling and activation of key transcription factors involved in the EMT in colon cancer cells, but with limited impact on the metastatic potential in immunocompromised mice." (PMID 35260660, 2022). "In a panel of five colon cancer cell lines, RNAi-mediated TIMELESS depletion for 72 hours ubiquitously caused an increase in γH2AX, a marker of DNA damage; however, the cell lines demonstrated variable levels of H2AX phosphorylation with HCT15 cells resulting in a relatively small increase." (PMID 30629587, 2019). "The results showed that PD treatment increased the fluorescence level of γ-H2AX in both RKO and LoVo cells, suggesting that PD induces DNA damage in colon cancer cells." (PMID 39850563, 2024). "We found that, in colon cancer cells, HG attenuated ADR-induced ROS production that consequently diminished ADR-induced H2AX phosphorylation and micronuclei (MN) formation." (PMID 31384396, 2019). "In colon cancer cells, WDR5 decreases the phosphorylation of the histone protein H2AX and induces H3K4 trimethylation, leading to colon cancer cell proliferation and survival, and WDR5 depletion sensitizes colon cancer cells to radiation-induced DNA damage." (PMID 30488017, 2018). "WT cells also showed phosphorylation of H2AX at 48 h, indicating that the cells are indeed detecting the MNU-induced damage in a similar timeframe to the colon cancer cells." (PMID 19623177, 2009). "We further texted whether the change in POU2F1 expression could modulate the H2O2-induced γ-H2AX and PCNA expression in colon cancer cells." (PMID 34997215, 2022). "In agreement with our observations, no staining for γ-H2AX was observed in lymphoma cells or colon cancer cells after treatment with oxaliplatin, whereas cisplatin treatment resulted in γ-H2AX foci." (PMID 32967255, 2020). "We measured γ-H2AX in RKO cells, a line of poorly differentiated colon carcinoma cells." (PMID 26756218, 2016). "Similarly, Zhang and colleagues found in a colon cancer cell line, knocking down ERCC1 protein expression increased the response to cells to CPT-11 in combination with ABT-888 as measured by γ-H2AX phosphorylation." (PMID 25774912, 2015).
colon carcinoma (continued). "WDR5 depletion reduced H3K4Me3 and increased phosphorylation of H2AX in HCT116, SW620, and RKO colon cancer cells; however, OICR-9429 treatment did not recapitulate these effects in all cell lines potentially explaining the reduced toxicity of OICR-9429 treatment as compared to WDR5 depletion." (PMID 29925347, 2018).
glioblastoma (38 papers, 2011 to 2025). The most malignant astrocytic tumor (WHO grade IV). "Mechanistically, suppression of protein arginine methyltransferase 5 (PRMT5) attenuates the expression of RNF168 in methylthioadenosine phosphorylase (MTAP)-deficient glioblastoma cells, contributing to the destabilization of H2AX by SMURF2." (PMID 36694209, 2023). "In addition, significantly increased EA-induced DNA damage was confirmed in human glioblastoma cell lines U87 and U118 by determining the presence of the phosphorylated form of H2AX histone variant (γ-H2AX), which serves as a molecular marker of DNA damage." (PMID 38002335, 2023). "Additionally, the efficacy of radiotherapy was enhanced by dichloroacetate in glioblastoma cells, both strategies worked synergistically, in vivo and in vitro, to elevate mitochondrial ROS levels and γ-H2AX (a hallmark of DNA damage) in GBM cells." (PMID 27199982, 2016). "The increase in the phosphorylation level of H2AX (p-γH2AX (Ser 139)) due to the LCS1269 treatment in all tested glioblastoma cells was used as a readout and confirmation of DNA damage." (PMID 40649791, 2025). "Studies on glioblastoma cell lines, including M059J, have shown that γ-H2AX levels increase following exposure to ionizing radiation, indicating DNA damage, which is consistent with strong expression levels of the gene H2AFX encoding H2AX45." (PMID 41402400, 2025). "This is in agreement with previous studies showing that XPA depletion increases phosphorylation of H2AX in glioblastoma and bladder cancer." (PMID 39001501, 2024). "RNF168 also interacts with another E3 ubiquitin ligase, SMURF2, to modulate the stability of H2AX in glioblastoma cells." (PMID 36694209, 2023). "Specifically, silencing METTL3 enhanced the sensitivity of (glioblastoma stem cells) GSCs to γ-H2AX and efficient DNA repair, resulting in rescuing glioblastomas’ radiosensitivity." (PMID 36517820, 2022). "The increased circ-METRN upregulated DNA damage molecule γ-H2AX expression, but γ-H2AX level returned to normal at 24 h, indicating enhanced DNA damage repair process in radioresistant glioblastoma cells." (PMID 35843942, 2022). "The MN-γ-H2AX (+) increase in patient-derived glioblastoma cells treated with Ageritin, led us to suppose the involvement of reactive oxygen species as a potential cause of DNA lesions." (PMID 35458581, 2022). "ldrEXOs promoted the expression of γ-H2AX which has a key role in DNA double-strand break repair in glioblastoma radioresistance." (PMID 33867829, 2021). "And circ-METRN-abundant ldrEXOs increased the expression of γ-H2AX, indicating an efficient DNA damage-repair process in glioblastoma cells." (PMID 33867829, 2021). "The decrease in cell migration and elevated levels of γ-H2AX observed in CAP–TMZ compared to TMZ treatment alone supports an important role for αv integrins in glioblastoma." (PMID 33020527, 2020). "The results herein presented indicate that Coronarin D inhibits glioblastoma (U–251) cell growth by inducing cell cycle arrest at G1 phase after increasing expression of p21, likely mediated by the phosphorylation of H2AX." (PMID 31818017, 2019). "As we had access to samples from a dog that spontaneously developed a glioblastoma, we confirmed that Dbait induced phosphorylation of both H2AX and HSP90 in dissociated cells from the brain tumor." (PMID 31275862, 2019). "Coronarin D potently suppressed cell viability in glioblastoma U–251 cell line, and also induced G1 arrest by reducing p21 protein and histone H2AX phosphorylation, leading to DNA damage and apoptosis." (PMID 31818017, 2019).
glioblastoma (continued). "Our results are consistent with one report in glioblastoma cells that increased levels of γ-H2AX after imetelsat treatment." (PMID 28099140, 2017). "Irradiated glioblastoma cells in which autophagy is inhibited displayed more pronounced and prolonged foci of phosphohistone H2AX, a marker of DNA double-strand breaks." (PMID 27655644, 2016). "To confirm that RECQ1 has the same role in glioblastoma cells, we analyzed the extent of spontaneous γ-H2AX foci formation in control or RECQ1 siRNA transfected T98G and U-87 cells." (PMID 21752281, 2011). "We also show that acute depletion of RECQ1 by RNAi results in a significant reduction of cellular proliferation, perturbation of S-phase progression, and spontaneous γ-H2AX foci formation in T98G and U-87 glioblastoma cells." (PMID 21752281, 2011). "In addition, after co‐culturing with TAAs, transfer of si‐ALKBH7&APNG‐oe into glioblastoma cells resulted in reduced accumulation of γ‐H2AX after TMZ administration compared to the si‐ALKBH7 group." (PMID 38332576, 2024). "Furthermore, a concomitant increase in γ‐H2AX expression of glioblastoma cells can be observed after co‐culturing with si‐ALKBH7 TAAs." (PMID 38332576, 2024). "Treated with circ-METRN-abundant exosomes, γ-H2AX (radiation-induced phosphorylation of H2AX, a marker of DNA breaks) was highly expressed in glioblastoma cells, indicating an efficient DNA damage-repair process in glioblastoma cells." (PMID 36316715, 2022). "As expected, γ-H2AX staining increased rapidly following radiation and returned to basal level at 24 h in cells treated with ldrEXOs, indicating an efficient DNA damage-repair process in glioblastoma cells." (PMID 33867829, 2021). "For example, the combined treatment of cisplatin-tethered GNPs (50 nm) and irradiation significantly enhanced DNA DSBs, as evidenced by the enhanced density of γ-H2AX foci, resulting in the apoptosis of patient-derived treatment-resistant glioblastoma multiforme (GBM) cells." (PMID 32168899, 2020). "Moreover, the combined treatment delayed the resolution of γ-H2AX proteins, suggesting that iPA maintains DNA damage enhancing the radiosensitivity of glioblastoma cells." (PMID 31993371, 2019). "Hence, we further examined the H2AX phosphorylation status in glioblastoma cells after MINA53 knockdown using immunofluorescence." (PMID 30333481, 2018). "Similar to our present data, the irradiated glioblastoma CSCs (GBM CSCs) had a significant delay in the phosphorylation of H2AX and DNA-PKcs (phospho S2056) up to 72 h and 48 h after irradiation, respectively." (PMID 33673439, 2021). "We treated both glioblastoma cell lines with 30 μM of PUN and evaluated the expression of γ-H2AX and Ku70 through Western blotting." (PMID 37686085, 2023). "The TMZ-resistant cells showed decreased basal levels of γ-H2AX, which is in agreement with the acquisition of TMZ resistance in glioblastoma that is due to an increase in the levels of DNA repair enzymes such as MGMT." (PMID 33201894, 2020). "To evaluate the impact of NMDARs on the DNA repair capacity in glioblastoma cells, we used a well-established DSB-marker, the Ser139 phosphorylated histone H2AX (γH2AX) to stain for γH2AX in S/G2–phase LN229 cells." (PMID 30970642, 2019). "The ELISA showed that, with the exception of the glioblastoma cell line SF268, total H2AX values varied from approximately 20 to 180 pM per 1 x 104 cells/μL (left hand panel)." (PMID 28158293, 2017). "In the present study, we observed higher expression of APNG in glioblastoma cells after indirect co‐culturing with TAAs via ALKBH7‐mediated crosstalk, and APNG expression was negatively correlated with the level of DNA damage repair marker γ‐H2AX." (PMID 38332576, 2024).
glioblastoma (continued). "Furthermore, as a sensor of DNA double‐strand breaks (DSB) induced by TMZ, γ‐H2AX expression lowered obviously in either SNB19 or SF295 cells when co‐cultured with TAAs than that of glioblastoma cells without co‐culturing with TAAs." (PMID 38332576, 2024). "In addition, after TMZ treatment, glioblastoma cells expressing miR-486-3p had a significant decrease in the expression of MGMT and increase in the levels of phosphorylated histone H2AX (γ-H2AX, Markers of DNA double strand breakage) and cleaved caspase-3 compared with vector control cells." (PMID 32086739, 2020). "In our study, despite the presence of MN-γ-H2AX (+), DNA damage was not supported by either the deregulation of DDR enzymes ATM and DNA-PK or oxidative stress induction, since glioblastoma cells treated with antioxidant NAC did not revert the Ageritin-induced cytotoxicity." (PMID 35458581, 2022).
melanoma (38 papers, 2009 to 2025). A malignant, usually aggressive tumor composed of atypical, neoplastic melanocytes. "The anti-tumor effects of PTS on melanoma cells (Mel Im) were investigated by analyzing the expression of different pro-apoptotic and senescence-associated genes (Caspase-3, -7, -9, p16, p21), with the mRNA expression of H2AX as an indicator for DNA damage, apoptosis and senescence." (PMID 34360651, 2021). "Additionally, to further verify whether down-regulation of GADD45A could enhance DNA damage associated with cisplatin treatment in melanoma, we assayed for phosphorylated H2AX (γ-H2AX), an early phase marker of DNA double strand break (DSB)." (PMID 29515153, 2018). "Along with these results, phosphorylated histone γ-H2AX on serine 139 (p-γH2AX-S139), a sensitive molecular marker of DNA damage, was detected at baseline levels in wt cells and decreased in arg-ii−/− melanoma cells." (PMID 40177131, 2025). "Then, the DNA damage induced by IR in B16 and A375 melanoma cells was evaluated using immunofluorescence staining of γ-H2AX." (PMID 40585994, 2025). "FXT promotes the apoptosis process in melanoma cells by influencing the expression of key proteins such as γ-H2AX, Akt, BAX, Bad, and caspase-9." (PMID 38911391, 2024). "We observe an increase of γ-H2AX expression in melanoma cells following inhibition of PD-1/PD-L1 binding and immune cell-cancer cell interactions, indicating that DNA damage has been induced." (PMID 37156818, 2023). "Microscopic images showed an increase in γ-H2AX expression in all melanoma cells after they were treated with nanocomplexes and co-cultured with hPBMCs, indicating increased DNA damage." (PMID 37156818, 2023). "Its overexpression in UACC-257 melanoma cells increases cell growth, BrdU positive cells, γ-H2AX levels, normoxic HIF-1α expression, and decreased p27Kip1 expression." (PMID 35326089, 2022). "HDAC inhibitors added to radiation increase the duration of γ-H2AX and radiosensitivity of prostate and melanoma cells." (PMID 34696786, 2021). "Subsequently, the phosphorylation levels of γ‐H2AX were evaluated to measure the accumulation of double‐strand breaks (DSB) in metastatic melanoma cells treated with TMZ." (PMID 34709752, 2021). "The promyelocytic leukemia protein (PML), a protein implicated in cellular senescence in melanoma, is involved in the development of these SAHF, just like gamma-H2AX." (PMID 33562468, 2021). "Treatment of A2058 melanoma cells with NEO412 resulted in increased levels of γ-H2AX protein, indicating accumulation of DNA strand breaks over the course of 3-4 days." (PMID 30651933, 2018). "SG2000 also had significant in vivo antitumour activity against canine melanoma xenografts, and the comet and γ-H2AX foci methods were relevant pharmacodynamic assays." (PMID 26282406, 2015). "SG2000 has significant in vivo antitumour activity against canine melanoma tumour xenografts, and the comet and γ-H2AX foci methods are shown to be relevant in vivo pharmacodynamic assays for measuring DNA ICL and DNA damage response." (PMID 26282406, 2015). "In order to quantify the induction of phosphorylated H2AX (γH2AX) as a function of cell cycle in UV-irradiated melanoma strains, we employed a sensitive flow cytometry-based approach." (PMID 24416382, 2014). "In a study of melanoma cells irradiated with proton and lithium beams, it was reported that the size of γ-H2AX foci was an accurate parameter correlating the rejoining of DSBs induced by different types of LET radiation and radio sensitivity." (PMID 21888676, 2011). "On the other hand, the melanoma cells treated with hPBMCs and/or pre-treated with ND and co-cultured with hPBMCs exhibited little, if any, difference in fluorescent staining or immunoblotting bands of γ-H2AX." (PMID 37156818, 2023). "However, there are pro-apoptotic genes such as H2AX and p21 that are more strongly induced in melanoma cells after DMEM + FBS PTS treatment." (PMID 34360651, 2021).